TCF7 (transcription factor 7)
Description:
Transcriptional activator involved in T-cell lymphocyte differentiation. Necessary for the survival of CD4(+) CD8(+) immature thymocytes. Isoforms lacking the N-terminal CTNNB1 binding domain cannot fulfill this role. Binds to the T-lymphocyte-specific enhancer element (5'-WWCAAAG-3') found in the promoter of the CD3E gene. Represses expression of the T-cell receptor gamma gene in alpha-beta T-cell lineages (By similarity). Required for the development of natural killer receptor-positive lymphoid tissue inducer T-cells (By similarity). TLE1, TLE2, TLE3 and TLE4 repress transactivation mediated by TCF7 and CTNNB1. May also act as feedback transcriptional repressor of CTNNB1 and TCF7L2 target genes.
Synonyms: TCF-1
Tractability: PROTAC: ubiquitination databases record sites on it; a small molecule that binds it is known.
Gene: Protein-coding gene on chromosome 5 (134,114,681 to 134,151,865, forward strand). Ensembl gene ENSG00000081059.
Subcellular location: Nucleus
Subcellular location (Human Protein Atlas): Nucleoplasm
Pathways (Reactome):
Signal Transduction: Binding of TCF/LEF:CTNNB1 to target gene promoters; Ca2+ pathway; Deactivation of the beta-catenin transactivating complex; Formation of the beta-catenin:TCF transactivating complex; Repression of WNT target genes
Developmental Biology: Formation of axial mesoderm; Germ layer formation at gastrulation; Regulation of MITF-M-dependent genes involved in cell cycle and proliferation
Gene expression (Transcription): RUNX3 regulates WNT signaling
Immune System: Regulation of PD-L1(CD274) transcription
Gene Ontology:
Molecular function: beta-catenin binding; protein binding; sequence-specific double-stranded DNA binding; transcription cis-regulatory region binding; DNA-binding transcription factor activity, RNA polymerase II-specific; DNA-binding transcription repressor activity; RNA polymerase II cis-regulatory region sequence-specific DNA binding
Biological process: cellular response to interleukin-4; canonical Wnt signaling pathway; gamma-delta T cell differentiation; immune response; regulation of DNA-templated transcription; regulation of gamma-delta T cell differentiation; regulation of transcription by RNA polymerase II; immune system process; negative regulation of DNA-templated transcription; Wnt signaling pathway
Cellular component: nucleoplasm; nucleus; beta-catenin-TCF complex; chromatin
Genetic constraint (gnomAD): Loss-of-function variants: 19 observed, 44.66 expected, observed/expected ratio (o/e) 0.43, 90% interval 0.3 to 0.62. The synonymous counts are far from expectation, so gnomAD's model fits this gene poorly and the ratio says little. Missense variants: 547 observed, 475.2 expected, observed/expected ratio (o/e) 1.15, 90% interval 1.07 to 1.24. Synonymous variants: 245 observed, 194.76 expected, observed/expected ratio (o/e) 1.26, 90% interval 1.13 to 1.4.
Homologues: Orthologues: chimpanzee TCF7 (96% identical), macaque TCF7 (95% identical), mouse Tcf7 (93% identical), dog TCF7 (92% identical), pig TCF7 (90% identical), rat Tcf7 (89% identical), rabbit TCF7 (63% identical), guinea pig TCF7 (55% identical), zebrafish tcf7 (54% identical), tropical clawed frog tcf7 (53% identical). Paralogues in human: TCF7L2 (49% identical), LEF1 (47% identical), TCF7L1 (45% identical).
Diseases named in the same sentence as TCF7 in open-access papers:
TCF7 is named in the same sentence as 117 diseases in open-access papers, as found by Europe PMC text mining. Sharing a sentence is not in itself a finding about the gene and the disease. The quoted sentences say what the papers report.
melanoma (37 papers, 2014 to 2026). A malignant, usually aggressive tumor composed of atypical, neoplastic melanocytes. "In a melanoma study, it was suggested that the transcription factor TCF7 in CD8+ T cells was associated with improved response to ICI." (PMID 40954554, 2025). "The abundance of TCF7 + PD1 + CD8 T cells was associated with better response to PD-1 blockade in melanoma and non-small cell lung cancer." (PMID 38719809, 2024). "High Tcf7 promoter methylation in human melanoma samples is significantly associated with low Tcf7 expression level, suggesting a suppressive role for DNA methylation." (PMID 37459511, 2023). "Despite this, the importance of TME resident TPEX cells in human cancer can be highlighted by the fact that the abundance of Tcf7+ CD8+ T cells within the TME of melanoma patients is associated with responsiveness to ICI." (PMID 37139854, 2023). "TCF7+ CD8+ T-cell frequency has been linked with tumor regression or checkpoint inhibitor response in melanoma." (PMID 36860910, 2021). "A single cell analysis on TILs from 48 melanoma samples also implicated Tcf7 in positive outcomes to therapy." (PMID 32210968, 2020). "On the other hand, a high number of TCF7/CD8+ T cells in melanoma tumors has been associated with clinical responses to immunotherapy." (PMID 33117345, 2020). "Our findings demonstrate that high SLAMF6 expression is associated with better prognosis, expression of TCF7 (encoding T-cell factor 1), and increased gene signatures associated with conventional type 1 dendritic cells and effector function of T cells in melanoma and breast cancer." (PMID 38287061, 2024). "It has also been uncovered that tumors enriched with B cells have an increased presence of TCF7+ naive T cells and/or memory T cells, suggesting that B cell-rich TLSs play a critical role in shaping the immune microenvironment of melanoma." (PMID 40857744, 2025). "The results revealed that LINC00698 was essential for the maintenance of tumorigenicity of MSCs via regulating TCF7 expression by sponging miR-3132, offering novel insights into the pathogenesis of melanoma." (PMID 39068483, 2024). "In clinic, TCF7 was significantly upregualted in the melanoma tissues compared to the normal tissues." (PMID 39068483, 2024). "The melanoma patients with higher TCF7 expression level had a worse survival rate than those with lower TCF7 expression level." (PMID 39068483, 2024). "For instance, melanoma resident CD8+ TCF7+ cells, abundance of dysfunctional CD8 + T cells, and accumulation of exhausted T cells in melanoma correlated with improved responses to immunotherapies." (PMID 34663807, 2021). "Our results suggest that BRAF/MEK inhibition in melanoma patients allows an increased expansion of pre-existing melanoma-specific T cells by induction of T-bet and TCF7 in these." (PMID 33275172, 2021). "We also identified a TCF-7+ CD103+ CD8+ progenitor exhausted T cell population in the tumor stroma of human melanoma, which seems to be the equivalent to the progenitor exhausted Trm identified in mice." (PMID 33240271, 2020). "In their experiment, GP133-specific Tcf7+ or Tcf7- CD8 T cells were transferred into mice before B16-GP133 melanoma engraftment and vaccine administration." (PMID 32707692, 2020). "TCF-7+ progenitor exhausted T cells also seem to be the best marker of good prognosis, mainly documented for melanoma, but also for kidney and lung cancer patients." (PMID 33240271, 2020). "An enrichment in Tcf7 gene was also reported in tumor-infiltrating cells from melanoma patients after anti-PD-1/anti-CTLA-4 therapies." (PMID 32707692, 2020). "In both mouse and human melanoma tumors we observed that Tcf7+ Pdcd1+ Tpe were enriched in Slamf6 and depleted of Havcr2 and Entpd1, which encode Slamf6, Tim3, and CD39 cell surface proteins, respectively." (PMID 32174925, 2020). "Melanomas rich in TCF7 responded better and showed a longer overall survival rate than melanomas with lower expression of TCF713." (PMID 32089832, 2020).
melanoma (continued). "Additionally, frequency of TCF7-expressing CD8+ T cells in melanoma can correlate to positive response to ICB, whereas in advanced clear cell renal carcinoma patients, it failed to predict any clinical outcomes." (PMID 39211052, 2024). "Furthermore, TCF7 expression was linked to patient response, whereas CD39 and TIM3 co-expression were linked with resistance to ICI therapy in melanoma patients from the same study." (PMID 37176128, 2023). "Moreover, we analyzed the expression level of gene CD3E, CD4, CD8A, GZMB, NKG7, TCF7 and TRBC2, the well-known markers for CD8+ T cells, and they were all shown to have significantly higher expression level in melanoma patients with low risk." (PMID 34040608, 2021). "Similarly, an immunomodulatory effect of dasatinib on T cells has been associated with improved anti-tumor immunity, and BRAF/MEK inhibition in patients with melanoma leads to upregulation of TCF7 and expansion of melanoma-specific TIL." (PMID 33795428, 2021). "Moreover, B cell-rich melanomas displayed increased levels of transcription factor 7 (TCF7)+ naive and/or memory T cells, whereas T cells in tumors without tertiary lymphoid structures had a dysfunctional molecular phenotype." (PMID 33036192, 2020). "In addition, elevated frequencies of melanoma-infiltrating TCF7+CD8+ T cells are correlated with beneficial clinical outcome of anti-PD-1-treated patients." (PMID 32194568, 2020). "There was an increment of TCF-7+ PD-1+ CD8+ T cells in melanoma patients compared with CS." (PMID 33240271, 2020). "In addition, elevated frequencies of melanoma-infiltrating TCF7+CD8+ T cells were found to predict positive clinical outcome in an independent cohort of anti-PD-1-treated patients." (PMID 31557787, 2019). "scRNA‐seq was performed on 48 melanoma samples from patients treated with ICI; two major cell states of CD8+ T cells were identified, one of which is a TCF7+ group that showed upregulation of genes related to memory, activation and survival." (PMID 40954554, 2025). "This was consistent with the finding from our scRNA-seq analysis which identified SLAMF6+ cells expressing TCF7, effector- and memory-related genes, compatible to the subset of progenitor-exhausted T cells identified in the TME of melanoma patients." (PMID 38287061, 2024). "The lack of potential TRL clones identified in the TCF7+ axis of the CD8+ T cell atlas from biopsies is also compatible with a previous report showing that TCF7+ T cells in melanoma tend to be non-reactive bystanders." (PMID 39312285, 2024). "In contrast, transgenic overexpression of Tcf7 was found to stabilize PD-1lo stem-like cells and lead to more durable CD8+ T cell responses during Clone 13 infection and within the B16-GP33-41 melanoma models, implicating TCF-1 as a critical factor for the inception of Tex." (PMID 34354714, 2021). "The research further found that the transcription factor 7 (TCF7) is selectively expressed in memory-like T cells, so the ratio of CD8+TCF7+ to CD8+TCF7-TILs is strongly correlated with improved response and survival in melanoma patients treated with anti-PD-1." (PMID 32864131, 2020). "More recently, it has also been shown that in transplanted mouse models of melanoma and prostate cancer, CD8+ T cells primed in the tdLN acquired expression of the activation marker PD-1 while maintaining expression of the transcription factor Tcf7 and remaining negative for effector cytokines." (PMID 37139854, 2023).
breast cancer (34 papers, 2014 to 2025). A primary or metastatic malignant neoplasm involving the breast. "For instance, miR159 from Arabidopsis thaliana and soybean targeted transcription factor TCF7 in breast cancer to decrease expression of the MYC oncogene and attenuated the growth of breast cancer in vitro and in vivo." (PMID 40149445, 2025). "Several key markers, including p63, calponin, CD10, and T-cell factor 7 (TCF7), are considered crucial in inhibiting breast cancer development." (PMID 40563575, 2025). "By inhibiting TCF7, miR-159 can suppress cancer cell proliferation and attenuate the growth of breast cancer xenografts in mice." (PMID 40149445, 2025). "The involvement of RUNX1 and TCF7 in NK cell maturation has been well-documented, and TCF7 expression has been inversely correlated with lymphocyte exhaustion in human breast cancer." (PMID 40443661, 2025). "Further mechanistic studies revealed that MIR159 directly targets the TCF7 (Transcription Factor 7) gene in human breast cancer cells." (PMID 41393953, 2025). "In summary, we suggest that LEF1, TCF3,TCF4, and TCF7 have the potential to bebiomarkers in breast cancer clinics." (PMID 38100720, 2023). "Regarding the biomarker potential in breast cancer, our resultssuggest that LEF1, TCF3, TCF4, and specially TCF7, have significant diagnostic valueto distinguish breast cancer patients from healthy individuals and a role insubtyping insight." (PMID 38100720, 2023). "For example, the plant-derived miR-159 suppressed the growth of breast cancer cell via cross-kingdom regulation of the human transcription factor 7 (TCF7) gene." (PMID 34221971, 2021). "TCF7 protein was identified to be highly expressed in various cancers, such as lung cancer, pancreas cancer, and breast carcinomas." (PMID 34172072, 2021). "In breast cancer patients, the cooperation of AF1q with TCF7 led to the transcription of CD44, which is a WNT target gene that is essentially involved in tumor progression and epithelial-to-mesenchymal transition." (PMID 31671695, 2019). "In contrast, in metaplastic breast cancer a variable fraction of cancer cells expressed p63 or TCF7 or both proteins with squamous tumors having the highest frequency of p63+TCF7+ cells." (PMID 31519911, 2019). "For example, miR-159 derived from plants was detectable in human sera and inhibited breast cancer growth by targeting the human transcription factor 7 (TCF7) gene." (PMID 30967999, 2019). "By targeting 3′UTR of transcription factor 7, miR159 significantly suppressed breast cancer cell growth in vitro and in vivo." (PMID 29659501, 2018). "Plant derived miR159 significantly suppressed breast cancer cell proliferation by targeting transcription factor 7 (TCF7)." (PMID 29112983, 2017). "Although TCF-7 expression in breast cancer cells is largely unexplored, TCF-7 is activated in colorectal cancer, leading to metastatic behavior by overproduction of lymphoid tyrosine protein kinase p56." (PMID 26008979, 2015). "Our previous and current works pivotally connect two critical regulatory axes, GATA3/miR29b and miR29b/AF1q/TCF7/CD44/KISS1, associated with the Wnt pathway for breast cancer metastasis." (PMID 26079538, 2015). "The distribution of different TCF7 isoforms was found to vary between tumors and normal tissues in colon cancers or mammary tumors." (PMID 26289446, 2015). "Targets TCF7 and inhibits the growth of breast cancer cells." (PMID 41393953, 2025). "We found that SLAMF6 expression was highly correlated not only with the expression of T-cell markers (CD3E, CD8B, CD8A, and CD4) but also with upregulation of TCF7, PDCD1 encoding PD-1, GZMK, and effector-associated genes including IFNG and PRF1 in breast cancer." (PMID 38287061, 2024).
breast cancer (continued). "A synthetic plant-derived miR-159 mimic was able to inhibit breast cancer cell proliferation by targeting the transcription factor TCF7, which is an effector of the Wnt signaling pathway, thereby reducing the level of MYC protein and inhibiting the growth of breast cancer cells." (PMID 38643232, 2024). "Furthermore, plant miR159, derived from either raw or cooked vegetables (e.g., broccoli, soybean), significantly suppressed breast cancer cell growth in vitro and in vivo by targeting transcription factor 7 (TCF7)." (PMID 39698025, 2023). "Moreover, BST2 also promotes invasion and migration of tamoxifen-resistant breast cancer cells MCF-7 via TCF-7." (PMID 31957537, 2020). "Moreover, in vitro and in vivo assay revealed 2′-O-methylated miRNA-159 suppressed the proliferation of breast cancer cells, especially triple-negative BC cells, by targeting TCF-7." (PMID 32209098, 2020). "More importantly, in vitro experiments performed by the mentioned group revealed that synthetic miR159 is capable of reducing the proliferation of breast cancer cells by targeting sequence of the 3′ untranslated region (UTR) of Transcription Factor 7 (TCF7) mRNA." (PMID 28025496, 2016). "Our findings indicate that breast cancer cells with a hyperactive AF1q/TCF7/CD44 regulatory axis in the primary sites may represent “metastatic founder cells” which have invasive properties." (PMID 26079538, 2015). "Therefore, targeting AF1q/TCF7/CD44 regulatory axis and its associated signaling molecules of the Wnt pathway may be a useful therapeutic strategy for breast cancer patients." (PMID 26079538, 2015). "Notably, p63 and TCF7—which typically co-express and co-localize—were much less frequently observed together in BRCA1 carriers, suggesting that these alterations in myoepithelial cells may contribute to their increased breast cancer risk." (PMID 40563575, 2025). "Bioinformatic analysis using cBioPortal v6.0.0, revealed a positive correlation between USP30-AS1 expression and several Wnt signaling components, including TCF7, WNT1, WNT10, and MMP7, in clinical breast cancer." (PMID 41614739, 2025). "scRNA-seq analysis of existing human breast cancer dataset demonstrates that subsets of T cells co-expressing SLAMF6, TCF7, memory- and exhaustion-related genes comparable to progenitor-exhausted T cells identified in pre-clinical models and human melanomas." (PMID 38287061, 2024). "Single-cell profiling of breast cancer tumor microenvironment reveals SLAMF6 expression overlaps CD8 T cells with a T-effector signature, which includes subsets expressing TCF7, memory and effector-related genes, analogous to progenitor-exhausted T cells." (PMID 38287061, 2024). "Mechanism study revealed that synthetic miR159 had the potential to inhibit the growth of breast cancer cells by aiming the region of nucleotide 1445-1470 and 1842-1870 in 3′UTR of TCF7, then resulting in the decrease of MYC protein levels." (PMID 34012461, 2021). "To find the relevance of the NUMB, TCF7, and LEF1 promoters to β-catenin/RAC1, we performed a ChIP assay using anti-β-catenin/anti-RAC1 antibody in both colon and breast cancer chromatin samples." (PMID 30650643, 2019). "Among the analyzed cancer types, breast cancer was theonly one to present a down-expression of TCF7; no studies havepreviously appointed its low expression in breast tumors or analyzed the functionalimpacts decurrent of a loss of expression." (PMID 38100720, 2023). "With regard to plant miR159, which was shown to target transcription factor 7 (TCF7) in breast cancer, we were not able to confirm this prediction." (PMID 32292571, 2020). "E2F7(transcription factor 7), targeted by MIR424, miR-3666 and miR-26a, is highly expressed in multiple tumors such as endometrial carcinoma, breast cancer, colorectal cancer and glioma, indicating that E2F7 might constitute a potential therapeutic target." (PMID 31141819, 2019).
breast cancer (continued). "qRT-PCR analysis of mammary tumors demonstrated increased β-catenin transcriptional activity as judged by enhanced mRNA expression of β-catenin target genes (Cyclin D1, c-Myc, TCF-7, VEGF and MMP7) in the absence of VDR." (PMID 26008979, 2015). "Increased TCF-7 gene expression in MMTV-Ron VDR−/− tumors and decreased expression in response to 1,25D3 in R7 cells may suggest a mechanism by which VDR mitigates metastatic burden in Ron-overexpressing breast cancers." (PMID 26008979, 2015). "The expression of TCF7 seemed to be “shut off” around birth in non-lymphoid tissues, while TCF7 was over-expressed in malignant tumors, e.g. colorectal cancers, prostate cancers, or breast cancers, in addition to lymphomas and leukemia derived from T lymphocyte." (PMID 26289446, 2015). "The results show that high expression of TCF7, AXIN2 and WIF1 all predict shorter relapse-free survival (RFS) in HER2-amplified breast cancer, but longer RFS in HER2-non-amplified disease." (PMID 34003256, 2021).